LINC01679 (long independently transcribed non-coding RNA 1679)
Synonyms: TCONS_00029157
Gene: Long non-coding RNA gene on chromosome 21 (43,358,055 to 43,365,330, reverse strand). Ensembl gene ENSG00000237989.
Diseases named in the same sentence as LINC01679 in open-access papers:
LINC01679 is named in the same sentence as 3 diseases in open-access papers, as found by Europe PMC text mining. Sharing a sentence is not in itself a finding about the gene and the disease. The quoted sentences say what the papers report.
prostate carcinoma (1 paper, 2023). A carcinoma that arises from epithelial cells of the prostate gland. "LINC01679 serves as a molecular sponge for miR-3150a-3p in prostate cancer." (PMID 37025585, 2023). "On the other hand, LINC00893, LINC01679, MIR22HG, RP1-59D14.5, MAGI2-AS3, NXTAR, FGF14-AS2 and ADAMTS9-AS1 are among lncRNAs that act as tumor suppressors in prostate cancer." (PMID 37025585, 2023).
tumor (3 papers, 2021 to 2023). "According to our results, LINC01679 depletion promoted cell proliferation, metastasis, tumor growth, and inhibited cell apoptosis in vivo and in vitro, which was also associated with poor survival." (PMID 34900992, 2021). "Nude mouse tumor xenograft was established to examine LINC01679’s oncogenicity within PCa cells." (PMID 34900992, 2021). "However, the function of LINC01679 in tumor progression has not been studied yet." (PMID 34900992, 2021).
cancer (2 papers, 2021 to 2022). A tumor composed of atypical neoplastic, often pleomorphic cells that invade other tissues. "In this study, LINC01679 was associated with increased risk for AML, suggesting that LINC01679 may have distinct roles in various cancer types." (PMID 36276132, 2022). "LINC01679’s function in cancer together with the related mechanism has not been reported." (PMID 34900992, 2021).